CRB1 (crumbs cell polarity complex component 1)
Diseases named in the same sentence as CRB1 in open-access papers (continued):
Sharing a sentence is not in itself a finding about the gene and the disease.
macular holes (2 papers, 2025). A hole in the macula of the retina. "When comparing the prevalence of specific genes and comorbidities, we found the following associations in AR RP: CRB1 was statistically associated with ERM (p = 0.003), EYS with cataract (p = 0.001), PROM1 with CNV (p = 0.0026), and USH2A with macular hole (p = 0.01)." (PMID 40725401, 2025). "CRB1 was statistically linked to epiretinal membrane (ERM) (p = 0.003), EYS with cataract (p = 0.001), PROM1 with choroidal neovascularization (CNV) (p = 0.0026), and USH2A with macular hole (p = 0.01)." (PMID 40725401, 2025). "In cases of CRB1-retinopathies where retinal lamination and scaffolding is affected due to abnormal function of both photoreceptors and Muller cells, the presence of CMO or lamellar pseudoholes may contraindicate subretinal injection due to the risk of complications like macular hole formation." (PMID 40243434, 2025).
Telangiectasia (2 papers, 2015 to 2017). Telangiectasias refer to small dilated blood vessels located near the surface of the skin or mucous membranes, measuring between 0.5 and 1 millimeter in diameter. "The BN-J rat (a mutant line of Brown Norway rat with a mutation in Crb1) develops an early-onset RP phenotype and telangiectasia." (PMID 28424578, 2017).
cyst (1 paper, 2022). A sac-like closed membranous structure that may be empty or contain fluid or amorphous material. "The cyst-like lesions in both Tvrm266 and Tvrm323 mice may be useful for understanding the origin of and testing treatments for macular and foveal retinoschisis associated with CRB1 variants." (PMID 35675330, 2022).
cystoid macular edema (1 paper, 2023). An autosomal dominantly inherited cystoid macular edema manifesting with macular atrophy, strabismus and, sometimes, pericentral retinitis pigmentosa. "In addition, three patients had cystoid macular edema (gene groups CRB1, AIP1, and RDH12)." (PMID 37240262, 2023).
Gliosis (1 paper, 2010). Gliosis is the focal proliferation of glial cells in the central nervous system. "Mice deficient for Crumbs homologue 1 (CRB1) develop gliosis after light exposure." (PMID 20808778, 2010).
macular degeneration (1 paper, 2012). Loss of vision in the central portion of the retina (macula), secondary to retinal degeneration. "Here we report the first finding of a heterozygous nonsense mutation in CRB1 in an individual with macular degeneration." (PMID 22863181, 2012).
macular edema (1 paper, 2012). "A thickening of the fovea (without the cavitations associated with macular edema) observable by OCT in this participant is consistent with other cases of CRB1-related disease." (PMID 22863181, 2012).
neuroblastoma (1 paper, 2019). Neuroblastoma (NB) is the most common solid, extracranial childhood tumor. "Overall, we found that downregulation of 7 genes (Crb1, Lrrc9, Rcn1, Rtl1, Shisa3, Six6, St18) and upregulation of 2 genes (C1ql3, Slc18A1), are strongly predictive of favorable neuroblastoma outcome, consistent with delayed tumor development in Th-MYCN/Casp2−/− mice." (PMID 30670683, 2019).
Norrie disease (1 paper, 2021). A rare X-linked genetic vitreoretinal condition characterized by abnormal retinal development with congenital blindness. "However, mutations in retinal proteins encoded by Crumbs cell polarity complex component (CRB1) and Norrie disease pseudoglioma (NDP) genes is believed to be the possible pathogenesis." (PMID 34969406, 2021).
ocular hypertension (1 paper, 2025). Abnormally high intraocular pressure. "This highlights the importance of early genetic testing and comprehensive multimodal imaging in patients with CRB1-related retinopathies, emphasising the interplay between ocular hypertension, macular involvement, and retinal dysfunction." (PMID 40243434, 2025).
Onset (1 paper, 2013). The age group in which disease manifestations appear. "Mutations in CRB1 are a common cause of congenital or severe childhood-onset RD accounting for up to 10.1% of LCA/EORD patients and 2.7% in RP cases, as described in a recent meta-analysis of CRB1 mutations." (PMID 23379534, 2013).
Retinal atrophy (1 paper, 2013). A nonspecific term denoting wasting, especially as a result of degeneration, of the retinal pigment epithelium (RPE) and neurosensory retinal cells. "Since our mice do not have Crb-1 rd8 mutation, our results suggest that the deletion of Ccl2 and Cx3cr1 predisposes mice to retinal atrophy under aging and chronic light damage conditions more so than in the single CCL2 or CCR2 knockout mice." (PMID 23637822, 2013).
Retinal hemorrhage (1 paper, 2010). Bleeding located within the retina. "The integrity of the retinas was studied by SLO, which revealed acute retinal hemorrhage in 2 out of 4 wild-type and all Crb1−/− retinas (data not shown)." (PMID 20808778, 2010).
retinal ischemia (1 paper, 2025). A ischemic disease that involves the retina. "This phenomenon may be attributed to retinal ischemia secondary to photoreceptor degeneration and retinal pigment epithelium atrophy, potentially exacerbated by CRB1-induced disruptions in the blood-retinal barrier." (PMID 40416256, 2025).
retinopathies (31 papers, 2017 to 2026). "By providing high-resolution cross-sectional images of the retina, it allows for detailed assessment of retinal layers, thickness, and morphological changes associated with CRB1-associated retinopathies." (PMID 40149532, 2025). "The study aimed to evaluate CRB1-associated retinopathies using microperimetry (macular integrity assessment (S-MAIA) fast protocol) and spectral domain optical coherence tomography (SD-OCT)." (PMID 40149532, 2025). "The study extends previous investigations of CRB1-related retinopathy, highlighting the association of the p.(Pro836Thr) variant with African ancestry." (PMID 40590804, 2025). "Our findings of a significant increase in volume in parafoveal region and reduced foveal volume support the utility of this ratio in capturing the structural changes in CRB1-associated retinopathies." (PMID 40149532, 2025). "Specifically, foveal thinning combined with perifoveal thickening evidenced in the cohort support previous research on abnormal retinal architecture in CRB1-associated retinopathies." (PMID 40149532, 2025). "This study describes macular sensitivity using the S-MAIA and structure using SD-OCT data in individuals with genetically confirmed CRB1-associated retinopathies stratified into MD, EOSRD/LCA, and CORD phenotypes." (PMID 40149532, 2025). "This is the first time to the authors’ knowledge that the fast (screening) protocol on the S-MAIA has been used in patients with CRB1-associated retinopathies, which allows rapid assessment of sensitivity and is easily integrated into a clinical trial setting." (PMID 40149532, 2025). "In African populations the p.(Pro836Thr) variant has a high allele frequency of 0.329% (gnomAD v4.1.0), and was recently recognized as a cause of CRB1 retinopathy in four families." (PMID 40590804, 2025). "In clinical trials aiming to address CRB1-associated retinopathies, the necessity for robust and reliable outcome measures is paramount." (PMID 40149532, 2025). "By addressing these limitations, future research can enhance the accuracy and applicability of structure–function analysis in CRB1-associated retinopathies." (PMID 40149532, 2025). "Eighteen individuals with CRB1-associated retinopathies were assessed (88% white, 55% male), including 10 patients with MD, five with EOSRD/LCA and three with CORD." (PMID 40149532, 2025). "In 18 participants with CRB1-associated retinopathies, the lamination of the retina was categorised into three grades." (PMID 40149532, 2025). "Our findings therefore challenge the current paradigm and raise important questions about the phenotypic variability of CRB1-associated retinopathies." (PMID 40725401, 2025). "The findings from this study were consistent with other literature regarding abnormal retinal architecture in CRB1-associated retinopathies." (PMID 40149532, 2025). "Biallelic pathogenic variants in the CRB1 gene are known to result in a diverse spectrum of retinopathies with phenotypic variability." (PMID 40590804, 2025). "Optical coherence tomography (OCT) shows abnormal retinal lamination and increased retinal thickness typical of CRB1 retinopathy due to the loss of “inter-cellular adhesion” that CRB1 provides to the retinal organization." (PMID 38790254, 2024). "Mutations in the CRB1 gene are associated with a diverse spectrum of retinopathies with phenotypic variability causing severe visual impairment." (PMID 38927596, 2024). "They will also help understand the progression of CRB1-associated retinopathies over time, inform clinical management strategies, and identify windows of opportunity for intervention." (PMID 38622537, 2024). "This study characterizes the largest cohort of patients with molecularly confirmed CRB1 retinopathy as of this writing, with 23 novel CRB1 variants identified." (PMID 36099972, 2023). "Retinal thickening and abnormal retinal architecture have been some of the most consistent findings in CRB1-associated retinopathies." (PMID 37762234, 2023).
retinopathies (continued). "In vitro models of CRB1 retinopathies in mouse (Crb1−/−) have shown a loss of integrity at the subapical region–adherence junctions at the outer limiting membrane with displaced photoreceptors in the subretinal space." (PMID 37762234, 2023). "In conclusion, this multinational investigation characterizes the largest cohort of patients with molecularly confirmed CRB1 retinopathy as of this writing, identifies novel CRB1 variants, and delineates genotype-phenotype correlations." (PMID 36099972, 2023). "On OCTA, the macular deep capillary plexus and choriocapillaris had a lower vessel density in eyes affected by CRB1-associated retinopathy when compared to healthy controls." (PMID 36769743, 2023). "Up to 150 mutations have been identified in CRB1 that cause retinopathies, a majority of which are located in the large extracellular domain of the protein." (PMID 29651238, 2018). "Variants in the CRB1 gene have long been associated with retinopathies, and more recently the CRB2 gene has also been shown to have possible clinical relevance with respect to retinopathies." (PMID 28424578, 2017). "In this study, we identified a statistically significant association between CRB1 mutations and the presence of ERM, a finding that diverges notably from previous reports which consistently emphasized CME as the predominant macular pathology in CRB1-associated retinopathies." (PMID 40725401, 2025). "Addressing these methodological limitations in future research, such as by improved fixation training protocols and robust participant retention strategies, will be crucial in optimising clinical trial designs and improving outcomes for patients with CRB1-associated retinopathies." (PMID 40149532, 2025). "Distinctive signs of CRB1-associated retinopathies include nummular pigmentation, fine yellow punctate deposits, preserved para-arteriolar retinal pigment epithelium, coarse and abnormal retinal lamination and thickened retina seen on spectral domain optical coherence tomography (SD-OCT)." (PMID 40149532, 2025). "The authors also noted that sensitivity analysis was hindered by scotoma regions that expanded over time within the cohort, highlighting the inadequacy of relying solely on the average of all testing loci for accurate assessment in people with CRB1-associated retinopathies." (PMID 40149532, 2025). "The cause for the phenotypic variability in CRB1-associated retinopathies is unknown, but might be linked to differences in CRB1 and CRB2 protein levels in Müller glial cells and photoreceptor cells." (PMID 37886604, 2023). "More than 300 causative variants have been reported to cause CRB1-related retinopathies." (PMID 37762234, 2023). "Fourth, retinal thickening and loss of lamination may be evident, another phenotypic clue suggestive of CRB1-associated retinopathy." (PMID 29391521, 2018). "Characteristic features of CRB1-associated retinopathy include early onset maculopathy, loss of retinal lamination with increased retinal thickness, nummular intraretinal pigmentation, preservation of the para-arteriolar retinal pigment epithelium, and the presence of macular cysts." (PMID 29391521, 2018). "Finally, we discuss the current state of adeno-associated virus-mediated gene therapy and how it can be applied to treat retinopathies associated with mutations in CRB1." (PMID 28424578, 2017). "These structural changes underscore the centralised degeneration observed in our cohorts, particularly in the MD group, and suggest that foveal thinning combined with perifoveal thickening might serve as important markers for disease progression and severity in CRB1-associated retinopathies." (PMID 40149532, 2025). "Therefore, Crb1KOCrb2ΔRods mice might become important resources to test therapies for retinopathies due to mutations in the CRB1 gene." (PMID 31438467, 2019). "Further investigation into gut microbiome composition and intestinal permeability in humans with CRB1 retinopathies is warranted." (PMID 41998480, 2026).
retinopathies (continued). "This is particularly important in CRB1 retinopathy, an IRD with a strikingly wide phenotype range, where neural impacts across the full disease spectrum are not yet characterized." (PMID 42078489, 2026). "This is evident in cases of similar phenotypes such as with CRB1 retinopathy where cystic and schitic macular changes are also present." (PMID 40439747, 2025). "This is also a key factor to consider in order to design targeted therapies for the CRB1-related retinopathies." (PMID 41373703, 2025). "In conclusion, this study provides valuable insights into macular sensitivity and retinal architecture in individuals with CRB1-retinopathies, highlighting significant abnormalities compared to healthy controls." (PMID 40149532, 2025). "Hence, conducting pointwise sensitivity analysis across various luminance levels in a broad spectrum of CRB1-associated retinopathies could inform genotype–phenotype correlations and their changes over time, which are crucial for precise therapeutic interventions." (PMID 40149532, 2025). "As gene therapy for CRB1-retinopathies is underway, key aspects to consider before treatment should include evaluating the patient’s natural history, and with that, the therapeutic window." (PMID 40243434, 2025). "In contrast, additional deletion of CRB2 in the CRB1 knockout retina exacerbates the retinal phenotype, suggesting that CRB2 putatively acts as a modifying factor of human CRB-associated retinopathies." (PMID 38802833, 2024). "Distinctive features of CRB1 retinopathies are nummular pigmentation, fine yellow punctate deposits, preserved para-arteriolar retinal pigment epithelium (PPRPE) and coarse and thickened retina, with some cases presenting with a Coats-like vasculopathy." (PMID 37762234, 2023). "Biallelic pathogenic variants in the Crumbs cell polarity complex component 1 gene (CRB1, OMIM #604210) result in a diverse spectrum of retinopathies with phenotypic variability." (PMID 37762234, 2023). "This is the first study to provide detailed analysis of the transcriptome for CRB1 retinopathy with corresponding correlation to the epigenome." (PMID 36656098, 2023). "Sixty-nine patients with molecularly confirmed CRB1-related retinopathy from 63 unrelated families were identified from the Moorfields Eye Hospital, London." (PMID 37762234, 2023). "This retrospective study is the first to report the presence of FH in a molecularly confirmed CRB1-related retinopathy cohort following qualitative and quantitative SD-OCT analyses." (PMID 37762234, 2023). "Studies in CRB1 retinopathies have shown thickening and coarse lamination of retinal layers resembling an immature retina." (PMID 37762234, 2023). "Its role in foveal development has not yet been described; however, this retrospective study is the first to report foveal hypoplasia (FH) presence in a CRB1-related retinopathy cohort." (PMID 37762234, 2023). "Models that mimic mild retinopathies include the Crb1-knockout (Crb1−/−) mouse, the Crb1C249W/− knock-in mouse, the naturally occurring Crb1rd8 mouse, and the Müller glial cell-specific Crb2PdgfrαCre knockout mouse." (PMID 28424578, 2017). "To date, limited genotype–phenotype correlations have been established in CRB1 retinopathies." (PMID 40243434, 2025). "Then, we hypothesize that CRB2 gene might be a crucial candidate modifier for the severity of CRB1-associated retinopathies, and moderate levels of CRB2 could partially protect against the degeneration caused by CRB1 deficiency." (PMID 38802833, 2024). "Each had a retinal phenotype highly suggestive of CRB1-retinopathy." (PMID 36084042, 2023). "Upon querying a single cell RNA‐seq dataset, we showed pax2 highly expressing cell types clustered with early progenitor cells.Therefore, there remains the possibility that interplay between PAX2/6 and YAP1 influences the proliferative state seen in CRB1 retinopathy." (PMID 36656098, 2023).
retinopathies (continued). "More than 300 causative variants have been reported in CRB1‐associated retinopathy with no clear genotype–phenotype correlation." (PMID 36656098, 2023). "Additionally, CRB1 retinopathies have coarse and thickened retinas, which make structural OCT grading for FH more difficult." (PMID 37762234, 2023). "Modulation of this pathway may act as a possible therapeutic target for CRB1‐retinopathy." (PMID 36656098, 2023). "The large size of CRB1, occupying nearly all the AAV packing capacity, has made the development of a therapy for these retinopathies challenging." (PMID 36099972, 2023). "Therefore, it can be considered that CRB1 is essential for the maintenance, rather than assembly, of AJs between MCs and PRCs and that light may be an influential factor in the development of retinopathies." (PMID 38802833, 2024). "For example, a mild decrease in CRB levels leads to a relatively milder form of retinopathy, whereas greater reductions in CRB1 and CRB2 lead to early-onset RP; finally, a complete lack of CRB1 and CRB2 leads to LCA." (PMID 28424578, 2017).
vasculopathy (3 papers, 2016 to 2022). "In this case, we report the (first) occurrence of coat’s like vasculopathy in a patient diagnosed with LCA caused by a CRB1 mutation." (PMID 26872607, 2016). "On the other hand, the vasculopathy observed in CRB1 mutations could also be affected by microenvironmental factors." (PMID 38983543, 2022). "Similar to the presentation of CRB1-associated RP cases, coats-like vasculopathy could also be present in LCA with CRB1 mutations." (PMID 34440435, 2021). "On the other hand, the presence of coat’s like vasculopathy is highly suggestive of a CRB1 mutation, and CRB1 sequencing may be warranted in these patients." (PMID 26872607, 2016). "The genetic testing showed combined heterozygous missense mutation (paternal p.C469G and maternal p.R905Q) in CRB1 in the affected girl, which might account for her clinical features including macular retinoschisis, short axial length, and Coats-like vasculopathy." (PMID 38983543, 2022).
cancer (2 papers, 2018 to 2020). A tumor composed of atypical neoplastic, often pleomorphic cells that invade other tissues. "However, there are no any reports or laboratory data on the relationship between cancer and the following genes: GSG1L, CRB1, XKR8, ZNF680, ZNF284, and ZNF780B, which is part of the 17-gene signature." (PMID 32596394, 2020). "The other six genes (GSG1 like (GSG1L), crumbs cell polarity complex component 1 (CRB1), XK-related 8 (XKR8), zinc finger protein 680 (ZNF680), zinc finger protein 284 (ZNF284), and zinc finger protein 780B (ZNF780B)) are not mentioned in the cancer research area until now." (PMID 32596394, 2020).